SDHD (succinate dehydrogenase complex subunit D)
Diseases named in the same sentence as SDHD in open-access papers (continued):
Sharing a sentence is not in itself a finding about the gene and the disease.
tumor (continued). "While SDHB (1p36) and VHL (3p25) are associated with autosomal dominant disease, SDHD (11q23) and SDHAF2 (11q13) show a remarkable parent-of-origin effect whereby tumor formation is almost completely dependent on paternal transmission of the mutant allele." (PMID 28099933, 2017). "Despite the two PTC tumors with SDHC duplication showing increased SDHC mRNA expression, significantly reduced transcript expression of SDHC and SDHD was observed in the tumor samples compared with their paired normal tissue (both P<0.001)." (PMID 25694510, 2015). "Missense SDHx variants were identified in five of 37 pairs of samples (SDHB Ala3Gly n=2, Ser163Pro n=1, and SDHD His50Arg n=2), in both tumor and paired adjacent normal samples, confirming their germline origin." (PMID 25694510, 2015). "Our findings was supported by previous studies showing that the expression of SDHC and SDHD was reduced in tumor tissues and their roles as tumor suppressors have been identified." (PMID 26377099, 2015). "This would be a requirement specific for SDHD, as tumor development in SDHB, SDHC and SDHA appear to follow a two-hit kinetics." (PMID 24465590, 2014). "In this work, we made use of the inducible SDHD-ESR mouse, a conditional mutant in the SdhD gene, which encodes the small subunit of MCII, and that acts as a tumor suppressor gene in humans." (PMID 24465590, 2014). "Genes previously associated with neoplasia, CEBPA and SDHD, were decreased in expression (-1.5 – -2, p < 0.02)." (PMID 25023465, 2014). "In an attempt to force the initiation of tumor development, this strain was crossed with a KO for H19, a postulated imprinted modifier gene of SdhD– induced tumorigenesis." (PMID 25126540, 2014). "The identification of the SDHD subunit gene as the hereditary paraganglioma type 1 locus (PGL1) has uncovered unexpected links between SDH and tumor susceptibility, and highlighted the role of mitochondria in cancer." (PMID 17376234, 2007). "The first evidence for a role of SDHD in tumour development was obtained by the discovery of germline mutations in this gene as the cause for familial paraganglioma (PGL)." (PMID 15331017, 2004). "Based upon these results, we can exclude a role for SDHD as a classical tumour suppressor gene in NB." (PMID 15331017, 2004). "Additionally, the mitochondrial dysfunction identified in our analysis—marked by reduced ATP levels and increased ROS—reflects miR-210’s targeting of genes such as ISCU1/2 and SDHD, also reported in tumour cells and studied as hypoxia biomarkers." (PMID 41226989, 2025). "Additionally, we noted a decrease in the expression of the succinate dehydrogenase complex subunit D (SDHD) gene, which encodes a subunit of the mitochondrial enzyme responsible for succinate oxidation and is a well-known tumor suppressor." (PMID 37692839, 2023). "The PPGL arm of The Cancer Genome Atlas (TCGA) network undertook a comprehensive molecular characterisation of PPGL tumours using whole genome sequencing, transcriptomics and DNA methylation arrays for 173 cases of which 15 were SDHB and three were SDHD tumours." (PMID 38124114, 2023). "Overexpression of SDHD could significantly suppressed cell proliferation in vitro and tumor growth of HCC cells in vivo." (PMID 36968495, 2023). "Hypermethylation was higher in SDHB-mutated PPGL when compared to SDHA, SDHC and SDHD cases, which may explain the greater metastatic potential of SDHB-mutated tumours." (PMID 35938916, 2022). "A little more than half of tumors with the SDHD:p.H102R variant showed negative or weak diffuse staining of the SDHB subunits regardless of the sex of the patient or tumor localization." (PMID 36614070, 2022). "All patients had benign PGLs without evidence of metastases and no other SDHD-linked neoplasms were detected." (PMID 32098148, 2020).
tumor (continued). "Specific genotype-tumour risk associations provides a basis for novel investigative strategies into succinate dehydrogenase-related mechanisms of tumourigenesis and the development of personalised management for SDHB/SDHC/SDHD mutation carriers." (PMID 29386252, 2018). "Mutations in the succinate dehydrogenase (SDH) subunits (mainly SDHB and SDHD) lead to familial paraganglioma syndromes, and it has been noted that some of these tumours resemble the hypoxia-induced carotid body enlargement observed in individuals living at high altitudes." (PMID 29772792, 2018). "Our results lend further support to the notion that loss of an as yet unidentified locus (or loci) in 11p15 could contribute to tumor formation in SDHD, SDHAF2 and VHL-related PGLs/PCCs." (PMID 28099933, 2017). "The SDHD promoter was successfully sequenced in 451 tumor samples." (PMID 26327518, 2015). "In a large multicenter study, 62 of 69 PPGLs associated with mutations in SDHB/C/D/AF2 were negative for SDHB immunohistochemistry, whereas two SDHD-mutated tumours were scored as immunopositive." (PMID 26273102, 2015). "In all other cases, SDHD promoter mutations detected in the tumor were not present in the constitutional DNA, confirming they were acquired somatically." (PMID 26327518, 2015). "This was the case in 12 of the 16 tumors with SDHD promoter mutations affecting ETS binding sites and 4 of 5 tumor samples with SDHD promoter mutations not affecting ETS binding sites." (PMID 26327518, 2015). "Given that chromosomal synteny is not conserved between the two species, different chromosomal arrangement could therefore account for the differences in tumor appearance between SdhD-mutant humans and mice." (PMID 24465590, 2014). "SDHD is remarkable in showing an ‘imprinted’ tumor suppressor phenotype." (PMID 19956719, 2009). "Moreover, paragangliomas in patients with SDHD mutations have increased levels of HIF-2α and angiogenic factors, and the transcriptional profile of phaeochromocytomas with mutations in SDH subunits is similar to those seen in VHL-mutant tumours." (PMID 29772792, 2018). "Moreover, one tumor sample (T06) showed the somatic mutation T60A in the Succinate Dehydrogenase Complex Subunit B (SDHB), and interestingly the same patient also carried the R38P germline variant in the subunit D of the same complex (SDHD)." (PMID 29510530, 2018). "Immunohistochemical staining of the resected tissue may also suggest the presence of an SDHB/SDHD mutation; as tumours affected by these mutations will have negative staining for SDHB antibodies; this can be used to guide and streamline testing." (PMID 28965289, 2017). "In addition to the ETS binding site affecting mutations, SDHD promoter mutations not affecting the ETS binding elements were identified in 5 tumor samples." (PMID 26327518, 2015). "The constitutive activation of SdhD+/− glomus cells could precede CB tumor transformation." (PMID 25126540, 2014). "However, not all carriers of the SDHD mutation develop tumours, and inheritance is further complicated by maternal imprinting in gene expression." (PMID 19243216, 2009). "Further studies about the relationship of SDHC, SDHD, MTCO3, and NDUFV3 in MQ-induced anti-tumor effect will be applied." (PMID 32850358, 2020). "The authors also identified a missense variation in the SDHD gene (p.G12S), and IHC for the SDHB subunit showed faint and focal staining in the tumor tissue as compared to endothelial cells serving as internal controls." (PMID 28768491, 2017).
tumor (continued). "As loss of the non-mutated allele, i.e., LOH, seems to be a requirement for the tumor to arise in patients, the lack of development of tumors in these SdhD mutant strains could be explained by biological differences between human and rodents that impair spontaneous LOH to occur in these mice." (PMID 25126540, 2014). "Comparison of gene expression in Set 1 with the Sanger COSMIC dataset identified five down-regulated genes that have previously been confirmed to result in neoplasia; these included CEBPA, ERBB2, EXT1, PIM1, and SDHD." (PMID 25023465, 2014). "Multiple other genes encoding enzymes of the tricarboxylic (TCA) cycle are considered tumor suppressor genes including SDHB, SDHC, and SDHD (Succinate Dehydrogenase subunits B,C,D)." (PMID 21695080, 2011). "The overall median follow-up period of the subjects without a tumor was 5.54 years (1.08–17.7); 4.09 years (3.00–5.17) for SDHA, 5.92 years (2.33–13.33) for SDHB, and 4.83 years (1.08–17.17) for SDHD variant carriers." (PMID 39881751, 2025). "Tumour cells lacked SDHB staining at IHC but expressed SDHA; preserved SDHA IHC being a recognised phenomenon in SDHB, SDHC and SDHD pathogenic variants." (PMID 35938916, 2022). "123I-MIBG and 111In-pentetreotide scintigraphy should not be used as first-line imaging studies for initial tumour screening in asymptomatic SDHA, SDHB, SDHC or SDHD-pi mutation carriers (Grade A)." (PMID 34021277, 2021). "Although the SDHx-associated tumor spectrum is expanding, none of these malignancies have been directly linked to SDHB or SDHD variants." (PMID 30658386, 2019). "Four of these cases (ID69, ID66, ID67 and ID24) had a somatic variant in a known PPGL susceptibility gene (SDHB, SDHD, and 2x VHL) that was not present in the matched blood sample, indicating a sporadic tumor development in these cases." (PMID 31212687, 2019). "Increased levels of succinate in tumour samples from PPGL patients have been confirmed in a number of studies and high succinate to fumarate ratios suggested as a metabolic marker for the detection of SDHB/SDHD-related PPGL tumours." (PMID 29450727, 2018). "Importantly, the expression of SDHB is lost in all SDH-deficient neoplasms irrespective of the specific SDH subunit (SDHA, SDHB, SDHC, and SDHD) affected by a genetic mutation." (PMID 37999735, 2024). "Interestingly, patients with lymph node metastases showed significantly less SDHD expression in their tumor tissues in comparison to patients without metastases." (PMID 37899663, 2024). "Therefore, SDHB-absent tumor immunostaining suggests the presence of an inactivating germline SDHA, SDHB, SDHC, or SDHD followed by a somatic loss in the second allele of the gene." (PMID 36091175, 2022). "The tumor cells of SDHB-, SDHC-, and SDHD-mutated tumors were reported to show absence of SDHB immunostaining, whereas those of non-SDH mutated tumors showed strong SDHB immunostaining, and SDHB immunohistochemistry was found to have 100% sensitivity and 84% specificity in detecting mutations." (PMID 35300626, 2022). "However, SDHB IHC was not performed, and there was no SDHD genetic analysis described for the GIST, so it is difficult to say if the tumor was SDH-deficient." (PMID 28768491, 2017). "It is unclear whether germline carriers of the p.(Asp92Gly) SDHD mutation are at elevated risk of HNPGL and despite no tumours having been reported in the family, it is the opinion of their clinicians that surveillance was advisable and is ongoing." (PMID 26008905, 2015). "The specific SDHD mutation in the present case (p.Asp92Tyr), however, is relatively common - as it is found in almost 70% of 690 Dutch SDH-gene mutation carriers and has not been reported to be associated with spontaneous tumor regression before." (PMID 23083338, 2012).
cancer (40 papers, 2004 to 2026). A tumor composed of atypical neoplastic, often pleomorphic cells that invade other tissues. "The studies on mutations in the TERT and SDHD promoters highlight promoter-region mutations as important events that regulate the transcription of cancer regulatory genes by creating or abolishing transcription factor-binding sites." (PMID 33024276, 2020). "Malignant tumors occur in 5% of SDHD variant carriers compared to 33% in SDHB variant carriers." (PMID 38473347, 2024). "Additionally, high Th17 amounts combined with reduced SDHD levels in situ, as well as high serum succinate levels, were associated with cancer progression, suggesting Th17 cells as potential targets for immunotherapy." (PMID 37899663, 2024). "In 2000, the demonstration of SDHD being a tumour suppressor gene showed that Warburg view was actually true, at least in these very specific cases of inherited cancer predisposition, and that a defect in a central metabolic function could be the origin of cancer." (PMID 28471419, 2017). "SDHD upregulation has also been connected to worse outcomes for patients which indicates its role in cancer progression." (PMID 41751859, 2026). "Cancer cells often present with reduced expression of SDH subunits notably SDHB or SDHD resulting in succinate accumulation." (PMID 36344992, 2022). "The average age of PGL onset is 33 years with a prevalence of malignant tumour development of 4% for SDHD variation carriers." (PMID 33851515, 2021). "Hereditary PCC accounts for ~35% of cases and has been associated with germline mutations in several cancer susceptibility genes (e.g., KIF1B, SDHB, VHL, SDHD, RET)." (PMID 32354376, 2020). "In 2000, the description of the first mutations in the SDHD gene in patients with PPGL was a major breakthrough, not only in the understanding of PPGL tumorigenesis but in cancer in general." (PMID 28471419, 2017). "More studies on tumors, patients, and families are needed to inform whether SDHA pathogenic variants are associated with a specific cancer risk profile compared with SDHB, SDHD, or SDHC." (PMID 38885448, 2024). "Succinate accumulation in ccRC with decreased SDHD or SDHB expression was reported to enhance cancer cell invasion and metastasis by increasing DNA 5-methylcytosine (5mC) and suppressing 5-hydroxymethylcytosine (5-hmC) through inhibition of TET-2, resulting in global DNA hypermethylation." (PMID 36344992, 2022). "More recently, mutations in the regulatory regions of other cancer-related genes have been identified, including recurrent mutations in the promoters of PLEKHS1, WDR74, SDHD, and FOXA1 that alter gene expression levels, TF binding and that are associated with poor prognosis." (PMID 29456552, 2018). "There were no reports of potential SDHD-associated cancers in the immediate family although further information from extended family members was unavailable." (PMID 26008905, 2015). "However, further evidence is needed to support the haplo-insufficient involvement of SDHD in cancer." (PMID 15331017, 2004). "After assessing SDHs differential expression in pan-cancer, we found that SDHB, SDHC, and SDHD benefit COAD patients." (PMID 36949947, 2023). "Of the 27 patients who presented with multiple PGLs at the time of their genetic counseling consultation, 24 completed genetic testing and 19 (79.2%) tested positive for an LPV/PV in a hereditary cancer gene, all of which were in PGL/PCC genes (SDHD = 13, SDHB = 4, SDHC = 2)." (PMID 39539798, 2024). "The mechanism by which SDHB or SDHD expression is reduced in cancer cells is not entirely clear." (PMID 36344992, 2022).
head and neck tumors (4 papers, 2014 to 2022). "SDHD mutations are germline mutations that often occur in patients with multiple primary tumors including head and neck tumors." (PMID 36138281, 2022). "Amongst the four subunits of the SDHx and SDHAF2 genes that lead to paraganglioma syndromes (PGL) types 1 to 5, the highest risk of developing head and neck tumors is seen in relation to SDHD (PGL1) and SDHAF2 (PGL2)." (PMID 34072806, 2021). "SDHB mutations usually correlate with disease in the thorax, abdomen, or pelvis while SDHD mutations often manifest as head or neck tumors that are typically benign." (PMID 25298897, 2014). "Among the most impressive differences in TF activity, head and neck tumors display lower activities of FEV, TFAP2B and GATA2 and higher activities of TFEC, LEF1, and MAFB compared to SDHD-null tumors of other anatomical locations." (PMID 31234811, 2019).
mitochondrial disease (4 papers, 2015 to 2022). "Together the data presented here consolidate biallelic SDHD variants as a cause of mitochondrial disease due to mitochondrial complex II malfunction, and extend the variable associated clinical features." (PMID 34012134, 2021). "Just one mitochondrial disease patient is reported to harbour either SDHB or SDHD mutations and metabolic presentations have yet to be reported in association with SDHC or SDHAF2." (PMID 26008905, 2015). "This is the second report of recessive SDHD mutations resulting in a primary mitochondrial disease presentation and serves to characterise the biochemical, histochemical and functional consequences of our patient’s molecular genetic defect." (PMID 26008905, 2015). "Although complex II deficiencies are exceedingly uncommon (almost 2–8% of mitochondrial disease cases), either homozygous or heterozygous pathogenic variants are reported in SDHA, SDHB, and SDHD genes, leading to some primary mitochondrial disease such as Leigh or Leigh-like syndrome." (PMID 35160083, 2022). "Mutations in genes encoding for either structural subunits or assembly factors have been described (SDHA, SDHB, SDHD, and SDH assembly factor 1 (SDHAF1) for mitochondrial diseases; SDHD, SDHC, SDHB, SDHA, and SDHAF2 for hereditary paragangliomas)." (PMID 30030362, 2018).
autosomal dominant disease (2 papers, 2017 to 2018). Autosomal dominant form of disease. "Although SDHD and SDHB are both autosomal dominant diseases, the penetrance of SDHD-related PPGL is modulated by maternal imprinting." (PMID 30106970, 2018).
benign tumors (1 paper, 2023). "The other 4 SDHD mutation variants were also occult familial cases with benign tumors." (PMID 38144572, 2023).
SDHD also shares sentences with these, for which no sentence is quoted: infection (23 papers); lung carcinoma (4); acromegaly (3); pituitary tumor (3); tumor predisposition syndrome (3); carotid body paraganglioma (2); Cowden-3 syndrome (2); Genetic disorders (2); Leigh syndrome (2); medullary thyroid cancer (2); peripheral neuropathy (2); sterility (2); acral melanomas (1); adrenocortical adenoma (1); AIDS (1); clear cell renal cell carcinoma (1); embryonal cancers (1); Endocrine Neoplasia (1); endocrine tumors (1); familial hypercholesterolemia (1); Fanconi anaemia (1); glioma (1); glomus tumor (1); Granuloma (1); hepatoblastoma (1); hereditary cancer-predisposing syndrome (1); hereditary colorectal cancer (1); hereditary leiomyomatosis and renal cell cancer (1); Hodgkins lymphoma (1); hyperparathyroidism (1).
A further 30 diseases each share a sentence with SDHD in 1 paper.